TSLP (thymic stromal lymphopoietin)
Diseases named in the same sentence as TSLP in open-access papers (continued):
Sharing a sentence is not in itself a finding about the gene and the disease.
asthma (continued). "NEW & NOTEWORTHY TSLP is an epithelial-derived cytokine and a key regulator in the pathogenesis of severe uncontrolled asthma." (PMID 38469627, 2024). "The findings demonstrated the critical roles that TSLP and IL-33 play in the aetiology of asthma, which is typified by enduring airway inflammation and reduced lung function, indicating their potential as molecular targets." (PMID 39057040, 2024). "This central role of TSLP makes it potentially a useful target to treat allergic diseases, including asthma." (PMID 39267467, 2024). "Total IgE levels in serum and key cytokine levels in lung tissues were measured on day 14 to assess the efficacy of anti-TSLP antibodies in this asthma model." (PMID 39726595, 2024). "As previously discussed, in stable type 2-high asthma, the airway epithelium releases TSLP, IL-25, and IL-33, differentiating DC-activated TH2 cells." (PMID 39439788, 2024). "Biologics targeting the alarmins have gained increased attention, especially after the anti-TSLP antibody Tezepelumab demonstrated potential in patients with severe, uncontrolled asthma." (PMID 39057040, 2024). "Tezepelumab, which targets TSLP, has demonstrated efficacy in patients with T2-high asthma but also in phenotypes with lower levels of T2 inflammation." (PMID 39694589, 2024). "Blockage of TSLP signalling has been tested in clinical trials in several diseases such as asthma, atopic dermatitis, cat allergy and EoE." (PMID 39654685, 2024). "Treatment with anti-TSLP monoclonal antibodies showed efficacy in severe asthma and clinical trials for other eosinophilic diseases are ongoing." (PMID 38415254, 2024). "There is overwhelming evidence that TSLP is a master orchestrator of the immune response in asthma pathobiology." (PMID 38612858, 2024). "Our results unveil an intricate interplay between mast cell-derived proteases and TSLP with possible implications in asthma pathobiology." (PMID 38612858, 2024). "The type 2 inflammation in asthma is initiated by ‘alarmin cytokines’ such as TSLP, IL-25, and IL-33 secreted by BECs when sensitized by allergens." (PMID 38641850, 2024). "In our comprehensive review of biologic therapy switching in severe asthma, we specifically investigated the inclusion of tezepelumab-ekko, a novel therapeutic agent targeting TSLP." (PMID 38525773, 2024). "SHR-1905 is a humanized immunoglobulin G1 kappa monoclonal antibody that inhibits TSLP bioactivity, developed for the treatment of severe uncontrolled asthma." (PMID 39076593, 2024). "The primary target of TSLP in humans is dendritic cells; therefore, it appears to influence mostly the sensitization stage of asthma." (PMID 39118763, 2024). "These structures can disturb the integrity of bronchial epithelial cells, leading to the release of cytokines such as TSLP and IL-33, which can exacerbate the pathology of asthma." (PMID 39060923, 2024). "The utility of upper airway TSLP as a biomarker of severe asthma and to guide therapy warrants further study." (PMID 38999286, 2024). "Tezepelumab, a human monoclonal anti-TSLP antibody, is indicated as add-on treatment for individuals twelve years of age and older with severe asthma." (PMID 38878250, 2024). "The function of TSLP in response to increased concentrations of air pollutants or synthetic asthma triggers remains to be investigated." (PMID 38672419, 2024). "Among these cytokines, TSLP has been identified as a potential therapeutic target for severe asthma, leading to the development of a new biologic, tezepelumab (TZP)." (PMID 39552062, 2024). "The aim of this study was to investigate the influence of osthole (OS) on asthma-induced airway epithelial cell apoptosis and inflammation by restraining Th2 differentiation through suppressing TSLP/NF-κB." (PMID 39334402, 2024). "Anti-TSLP/anti-IL-13 biologic nanobody improved lung function and small airway dysfunction in asthma beyond those reported for monovalent IL-13 or TSLP pathway targeting." (PMID 39600699, 2024).
asthma (continued). "Regarding asthma, the most widely studied alarmins include IL-25, IL-33, and thymic stromal lymphopoietin (TSLP), which can all drive allergic inflammation via stimulation of TH2 cells and ILC2." (PMID 38878250, 2024). "In buccal Ck8+ epithelial cells in patient samples, there was a significant elevation in TSLP in GINA 5 asthma patients when compared to all other patients (p < 0.001 after adjusting for age and sex)." (PMID 38999286, 2024). "In severe asthma, TSLP plays a role in the development of corticosteroid resistance in airway inflammation through B-cell lymphoma-extra large expression by ILC2s." (PMID 39624446, 2024). "More in details, a long form of TSLP is typically produced by epithelial cells of asthma patients following viral infection." (PMID 39385131, 2024). "In clinical studies, anti-TSLP Ab treatment was shown to suppress asthma exacerbation in patients with severe asthma, inhibit eosinophilic inflammation in the airway, and to decrease the concentrations of IL-5 and IL-13 in serum." (PMID 39624446, 2024). "Overall, most physicians indicated preferring an anti-IgE for allergic asthma (59% of physicians), an anti-IL5 for eosinophilic asthma (87%), and an anti-TSLP for Type 2 Low asthma (68%)." (PMID 38637825, 2024). "There are differences in the level of TSLP expression by epithelial cells in individuals with asthma, atopy, and other allergic diseases compared to healthy controls." (PMID 38672419, 2024). "The dysregulated expression of and/or signaling by TSLP has been seen in a variety of inflammatory diseases, including atopic dermatitis (AD), food-hypersensitivity reactions, asthma, and cancer." (PMID 39201498, 2024). "In the asthma group, researchers have found an elevated TSLP mRNA expression in moDCs co-cultivated with both epithelium and moMφs, compared to moDCs alone." (PMID 38892164, 2024). "The exception is an anti-thymic stromal lymphopoietin (TSLP) human monoclonal antibody, which is also effective among individuals with non-T2 asthma." (PMID 39194521, 2024). "Within that frame, by selectively targeting TSLP tezepelumab has demonstrated to be extremely effective in every asthma patient." (PMID 39385131, 2024). "The prominent pro-inflammatory role of TSLP in the immune response of the epithelium has made it a target of therapy in asthma and other airway diseases characterized by immune dysregulation and epithelial changes." (PMID 38672419, 2024). "The potential interest of TSLP in melanoma care, as a prognostic factor or a pharmacological target, for instance, with anti-TSLP antibodies approved for asthma treatment, will require further evaluation." (PMID 39201498, 2024). "Understanding these differences is vital for developing targeted therapies for conditions such as asthma, allergic rhinitis, and atopic dermatitis, where TSLP-mediated pathways are key contributors to the pathogenesis." (PMID 38566968, 2024). "Three epithelial cytokines, i.e. thymic stromal lymphopoietin (TSLP), IL-33 and IL-25, known as “alarmins”, are central in asthma pathophysiology." (PMID 38609094, 2024). "Tezepelumab targets thymic stromal lymphopoietin (TSLP), an epithelial cytokine that has multifaceted effects on the initiation and persistence of inflammation in asthma." (PMID 39326921, 2024). "In a murine model of steroid-resistant asthma, multipotent ILC2s induced by IL-33, TSLP, and IL-2/IL-7 were found to contribute to steroid resistance." (PMID 39194521, 2024). "It targets alarmins, which are key epithelial inflammatory cytokines involved in the pathogenesis of asthma, and is a novel group of antibodies (TSLP, IL-25, and IL-33)." (PMID 38203353, 2023). "In this perspective, new clinical trials recently investigated new biologics as Tezepelumab, an anti-TSLP, and its ability to reduce the annualized rate of asthma exacerbations and to greatly improve lung function compared to placebo." (PMID 36830772, 2023).
asthma (continued). "There are three epithelial cell-derived cytokines such as IL-25, TSLP, and IL-33 known to mediate Th2 inflammation and IL-33 has been identified to initiate type 2 responses in asthma in response to the clinically relevant allergens including HDM." (PMID 37237381, 2023). "In contrast with blockage alone, the combined blockade of IL-25, IL-33, and TSLP has been shown to further inhibit airway remodeling and inflammation in a mouse model of asthma." (PMID 38082335, 2023). "An example is thymic stromal lymphopoietin (TSLP), a factor that promotes T helper cell (TH2) responses associated with various inflammatory diseases, including allergic inflammation, asthma, and chronic obstructive pulmonary disease." (PMID 37379383, 2023). "Tezepelumab, a TSLP antagonist used for asthma and atopic dermatitis, has a mechanism of action that targets the top of the inflammatory cascade, and a recent clinical trial has started to evaluate its role in improving outcomes for EoE patients." (PMID 37765327, 2023). "TSLP, a pleiotropic cytokine, is a key factor in the pathogenesis of asthma, and elevated TSLP levels have been correlated with enhanced levels of TNF-α and Th2 cytokines." (PMID 37569890, 2023). "Our finding that montelukast increased IL25, IL33, and TSLP expression supports the reduced effectiveness of LTRAs in terms of the clinical outcomes of asthma." (PMID 36674744, 2023). "TSLP is a pleiotropic cytokine that plays a pivotal role in the development and advancement of allergy and asthma." (PMID 37628907, 2023). "For example, tezepelumab, the first biological drug that targets TSLP, was recently approved for the treatment of severe asthma in the United States, European Union, Japan, and several other countries." (PMID 37109237, 2023). "Recently, tezepelumab (an anti-TSLP antibody) was found to lower the exacerbation risk, increase the FEV1, and enhance asthma control and health-related quality of life in a phase 3 trial in patients with severe uncontrolled asthma." (PMID 36979498, 2023). "Since TSLP plays a pivotal role in initiating and perpetuating allergic responses, it can be a crucial target for allergic diseases such as asthma, eczema, and allergic rhinitis." (PMID 37630370, 2023). "The emergence of lfTSLP as a central orchestrator of type 2 responses capable of initiation of inflammation and allergy has preferentially positioned a new therapeutic targeting of the TSLP-mediated signalling in asthma and atopic diseases." (PMID 37628907, 2023). "This anti-thymic-stromal-lymphopoietin (TSLP) biologic is also indicated for both T2-high and T2-low asthma." (PMID 36836079, 2023). "Thymic stromal lymphopoietin (TSLP), is critical to induce the activation of both innate and adaptive immune responses in asthma." (PMID 37680747, 2023). "According to our data, and those obtained from experimental studies, TSLP seems to play a key role in asthma inception after respiratory viral infections." (PMID 36694181, 2023). "While most of the FDA-approved biological therapies target pathways of T2 inflammation downstream of T-helper 2 cell activation, modest asthma control has led researchers to study upstream alarmin cytokines, including IL-25, IL-33, and TSLP." (PMID 38259298, 2023). "Tezepelumab, a subcutaneously administered anti-TSLP monoclonal antibody has been licensed for severe asthma." (PMID 37265457, 2023). "We also evaluated by qRT-PCR the effect of BT on the expression of IL-25, IL-33, TSLP and hBD2; typical asthma-related alarmins or antimicrobial peptides in BECs." (PMID 37996952, 2023). "Further real-world studies are eagerly awaited to shed more light on the potential clinical utility of targeting TSLP in asthma therapy." (PMID 37752512, 2023). "Although the role of omentin in dengue is not known, omentin (intelectin) was shown to induce allergen induced production of IL-25, IL-33 and TSLP in asthma and atopic dermatitis." (PMID 37676889, 2023).
asthma (continued). "Genetic variations, including TSLP single nucleotide polymorphism rs1837253, result in the onset of asthma, and high levels of TSLP and Th2 cytokines in the lung are observed in the airway in asthma patients." (PMID 37165746, 2023). "Studies of ILC2 sensitivity toward corticosteroid treatment, which is the mainstay therapy for asthma, showed that thymic stromal lymphopoietin (TSLP)/signal transducer and activator of transcription 5 (STAT5) signaling mediated steroid resistance in ILC2s22." (PMID 37696890, 2023). "Thymic stromal lymphopoietin (TSLP) is an epithelial cell-derived cytokine that contributes to allergic inflammation, including atopic dermatitis and asthma." (PMID 37660072, 2023). "Our previous study showed that CpG oligodeoxynucleotide (CpG-ODN) inhibits thymic stromal lymphopoietin (TSLP)-dendritic cells (DCs) to reduce Th2/Th17-related inflammatory response in smoke-related asthma." (PMID 36834541, 2023). "have identified intelectin (ITLN) knockdown suppressed expression of IL-33, IL-25, and TSLP expression in asthma and atopic dermatitis models." (PMID 37153553, 2023). "T2 high asthma is primarily driven by cytokines (IL-4, IL-5, IL-13), eosinophil alarmins (IL-25, IL-33, thymic stromal lymphopoietin [TSLP]), and Immunoglobulin E (IgE)." (PMID 37189529, 2023). "Thymic stromal lymphopoietin (TSLP) is an essential modulator of asthma pathogenesis, mainly produced by human epithelial cells, keratinocytes, and bronchial smooth muscle cells." (PMID 36834541, 2023). "In another airway hypersensitive state, recombined IL-37 (rIL-37) reduced airway inflammation and ameliorated asthma progression through suppressing thymic stromal lymphopoietin (TSLP) expression in lung tissues via inhibiting NF-κB and ERK1/2 pathways." (PMID 37928545, 2023). "In the next part of this review, we will discuss in more detail the established and under evaluation therapeutic approaches for SA management, focusing on the essential role of TSLP in asthma regulation." (PMID 37108740, 2023). "Our results showed, for the first time, that infants admitted for bronchiolitis, who later developed asthma, with need of chronic treatment, by the age of 4, were significantly more likely to have nasal TSLP detection at admission." (PMID 36694181, 2023). "Tezepelumab, a humanized monoclonal antibody targeting the upstream asthma inflammatory mediator Thymic Stromal Lymphopoietin (TSLP), is a potential treatment option for severe non-T2 asthma patients." (PMID 37794472, 2023). "The T2-high asthma endotype involves allergy-mediated responses that involve eosinophils, interleukin (IL)-4, IL-5, IL-13, IgE, thymic stromal lymphopoietin (TSLP), leukotrienes, and prostaglandin D2 (PGD2)." (PMID 37048164, 2023). "Following these results, the US FDA granted tezepelumab breakthrough drug status for use in severe asthma patients, making it the first anti-TSLP mAb used in asthma therapy." (PMID 37334374, 2023). "In the current study, CpG-ODN treatment reduced the levels of TSLP and IL-33 in smoke-related asthma." (PMID 36834541, 2023). "Numerous asthma susceptibility genes, for instance, IL33, IL1RL1, MUC5AC, TSLP, CDHR3, and KIF3A, are expressed in the airway epithelium." (PMID 36832296, 2023). "Role of thymic stromal lymphopoietin in asthma: Our understanding of the airway epithelium in driving asthma pathogenesis has progressed extensively in recent years." (PMID 37063828, 2023). "Taken together, these results from phase 2/3 trials suggest that blocking the upstream alarmin TSLP with tezepelumab results in clinically meaningful improvements in asthma control in patients with T2-high asthma concerning exacerbations." (PMID 37259416, 2023). "In asthma, TSLP is increased in the airways of humans and rodents, and an anti-TSLP monoclonal antibody, tezepelumab, was effective and safe for the treatment of severe asthma in a phase 3 clinical trial." (PMID 37660072, 2023).
asthma (continued). "The role of TSLP in type 2 immune responses in allergic diseases, including asthma, has been extensively studied, and recent studies have revealed additional roles for this cytokine in infectious diseases, cancer, fat metabolism and inflammatory diseases." (PMID 37165746, 2023). "Tezepelumab is an anti-TSLP human monoclonal antibody that reduced exacerbation rates, increased lung function, and improved asthma control and quality of life in RCTs." (PMID 40980110, 2023). "TSLP expression is also higher in the airways of patients with asthma than in those of healthy controls." (PMID 36941691, 2023). "Its ability to address keratinocyte differentiation, skin barrier functions, and TSLP inhibition holds implications not only for AD but also for broader allergic diseases like asthma and eczema." (PMID 37630370, 2023). "Innate cytokines, known as alarmins, specifically TSLP, IL-25, and IL-33, are promising candidates for the development of novel biological therapies against severe asthma." (PMID 38203353, 2023). "Another asthma‐specific target is IL‐7R, which acts as a receptor for interleukin‐7 (IL‐7) and TSLP." (PMID 37186423, 2023). "The main goal of this study was to investigate the association of nasal detection of periostin and thymic stromal lymphopoietin (TSLP) during severe bronchiolitis with the development of asthma at 4 years of age." (PMID 36694181, 2023). "Allergen, chemical stimulation and viral infection can each trigger the production of TSLP from epithelial cells, resulting in airway inflammation and airway hyperresponsiveness, leading to the symptoms of asthma." (PMID 37165746, 2023). "TSLP is a cytokine mainly derived from epithelial cells, which occupies an upstream position in the asthma inflammatory cascade." (PMID 37628907, 2023). "Due to this connection, dupilumab, an anti-IL4Rα mAb approved for asthma treatment, and tezepelumab an anti-TSLP mAb also approved for asthma treatment are also being tested in COPD patients with eosinophilia via randomised clinical trials." (PMID 37334374, 2023). "One such appealing therapeutic target is thymic stromal lymphopoietin (TSLP), an epithelial-derived cytokine with critical functions in allergic diseases, including asthma." (PMID 37108740, 2023). "In THP-1 cells, NAC inhibited ROS production induced by thymic stromal lymphopoietin (TSLP), a Th2-like cytokine involved in asthma pathogenesis." (PMID 37760016, 2023). "This helps in understanding the impact of TSLP in the development and/or exacerbation of COPD, and in what way TSLP affects lung pathophysiology in situations other than TH2-related asthma." (PMID 36830972, 2023). "Tezepelumab, a fully human monoclonal IgG2λ antibody currently indicated for the treatment of severe asthma, specifically binds human TSLP at the level of its ligation site for TSLPR, thereby impeding the TSLP-TSLPR interaction." (PMID 37628907, 2023). "Recent evidence also demonstrated the potential role and effectiveness of new biological drugs directed against specific type 2 alarmin cytokines (i.e., thymic stromal lymphopoietin [TSLP], IL-25, and IL-33) in severe asthma." (PMID 36830772, 2023). "TSLP is one of the epithelium-derived alarmins, plays important roles in type 2 immunity and asthma." (PMID 36760534, 2023). "Other variables also associated with TSLP detection were intensive care unit (ICU) admission (p = 0.02) and siblings with asthma/atopy (p = 0.002)." (PMID 36694181, 2023). "Patients with asthma, in particular patients with severe asthma, show elevated levels of TSLP and TH2 cytokines in the airways." (PMID 36830972, 2023). "Currently, there has been an influx of biologic treatments for asthma targeting cytokines that are notable drivers for asthma exacerbation, such as tezepelumab (anti-TSLP), astegolimab (anti-ST2), itepekimab (anti-IL-33), and risankezumab (anti-IL-23)." (PMID 37377967, 2023).